VANGL2 (VANGL planar cell polarity protein 2)
Diseases named in the same sentence as VANGL2 in open-access papers (continued):
Sharing a sentence is not in itself a finding about the gene and the disease.
breast cancer (continued). "Here we report the overexpression of the Wnt/PCP core component VANGL2 in breast cancers with poor prognosis." (PMID 26754771, 2016). "Using cell culture and murine assays, we now demonstrate that VANGL2 is involved in breast cancer cell migration, anchorage-dependent and -independent cell proliferation as well as tumour growth." (PMID 26754771, 2016). "We have thus identified a previously uncharacterized VANGL2–p62/SQSTM1 complex in breast cancer cells." (PMID 26754771, 2016). "Taken together, these data show that overexpression of VANGL2 in breast cancer cells correlates with JNK activation and cell proliferation, which is sensitive to inhibition of the VANGL2–p62/SQSTM1 interaction." (PMID 26754771, 2016). "We find that p62/SQSTM1 is required to recruit and activate JNK in breast cancer cells through an evolutionarily conserved VANGL2–p62/SQSTM1–JNK signalling cascade." (PMID 26754771, 2016). "When membrane-permeant peptides were added to the culture media of breast cancer cells, a specific decrease in cell proliferation was detected in high VANGL2-expressing cells (SUM149 and HCC1806) with FITC-Tat-p62DN peptide, but not with the control peptide." (PMID 26754771, 2016). "Overall, these data suggest that VANGL2 overexpression participates in tumour growth in breast cancer cell lines." (PMID 26754771, 2016). "In our data set, 23% of breast cancers showed VANGL2 mRNA upregulation with a good correlation with gene amplification." (PMID 26754771, 2016). "Vangl1 mRNA has a broad expression in all tested breast cancer cell lines whereas Vangl2 mRNA is more selectively expressed and only detectable in a limited number of cell lines." (PMID 23029439, 2012). "To assess whether Vangl regulates the cytoskeleton in leader cells, we employed time-lapse microscopy of collectively migrating breast cancer cells depleted of Vangl2 and stably expressing FRET biosensors for cytoskeletal regulators Rac1 and RhoA." (PMID 37147680, 2023). "Here, we examine the contribution of Wnt/planar cell polarity (Wnt/PCP), one of the non-canonical Wnt signaling pathways and defined by the involvement of the tetraspanin-like proteins Vangl1 and Vangl2, to breast tumor cell motility, collective cell invasiveness and mammary tumor metastasis." (PMID 37147680, 2023). "Interestingly, SCRIBBLE and SMURF2 mRNAs are also over-expressed in several cases of basal VANGL2- or NOS1AP-amplified breast cancers but rarely in other subtypes." (PMID 36675340, 2023). "While alterations of VANGL1 and VANGL2 in breast cancer have been investigated, their function in normal breast development is still unknown." (PMID 31068622, 2019). "Another human hub gene, VANGL2, which was correlated with the EBV gene LMP-1, encodes a membrane protein involved in the regulation of planar cell polarity and its expression was shown to be related to breast cancer." (PMID 28415594, 2017). "VANGL2–JNK signalling is thus a potential target for breast cancer therapy." (PMID 26754771, 2016). "This blocking strategy may represent a more specific, and possibly, less harmful alternative to inhibit VANGL2–p62/SQSTM1–JNK signalling in VANGL2-overexpressing breast cancers." (PMID 26754771, 2016). "Here we find that the non-canonical Wnt/PCP VANGL2 gene is linked to a basal signature and is overexpressed in breast cancers with poor prognosis." (PMID 26754771, 2016). "With exception of VANGL2, up-regulation of the genes involved in Wnt signaling pathway, namely WNT5A, MSX2, TCF7L2 and TNFRSF11B, was confirmed in the validation set, further emphasizing the important role of the Wnt signaling pathway in PIK3CA-mutated breast cancer." (PMID 21209903, 2010). "These patterns include elevated Fzd2 in metastatic breast cancer, increased ORAI1 in basal-like breast cancer (BLBC), high expression of Vangl2 and ROR1 in BLBC, and overexpression of Syndecan in BC generally." (PMID 40804731, 2025).
breast cancer (continued). "To investigate the subcellular localization of VANGL2, we initially examined HCC1569 cells, a highly proliferative, HER2+ breast cancer cell line that expresses high levels of Vangl2." (PMID 38334614, 2024). "Vangl1 and Vangl2 knockdown and overexpression and Wnt5a stimulation were employed to manipulate Wnt/PCP signaling in a battery of breast cancer cell lines representing all breast cancer subtypes, and in tumor organoids from MMTV-PyMT mice." (PMID 37147680, 2023). "We determined that Wnt5a-mediated migration is ablated in VANGL2 knockdown breast cancer cells, demonstrating that Wnt5a specifically activates Vangl-dependent Wnt/PCP signaling in breast cancer cells." (PMID 37147680, 2023). "VANGL2 and NOS1AP are located at neighboring loci 1q23.2 and 1q23.3 and are amplified in 8.8% and 9.1% of breast cancer cases of TCGA cohort, respectively." (PMID 36675340, 2023). "Effective deletion of Vangl2 in mammary tumors of Vangl2fl/fl;MMTV-Cre±;MMTV-NDL± (Vangl2fl/fl/NDL) mice relative to Vangl2fl/fl;MMTV-NDL± (Vangl2+/+/NDL) mice was confirmed by qPCR." (PMID 37147680, 2023). "Two of the four breast cancer cell lines with SCRIB, VANGL2 and NOS1AP concomitant amplification in the CCLE collection display sensitivity to porcupine inhibitors, and one of them also shows sensitivity to drugs affecting the PI3K/AKT/mTOR pathway." (PMID 36675340, 2023). "For example, Vangl2 binds p62/SQSTM1, an intracellular adaptor protein, in the late endosomal compartment, which engages JNK signaling and drives breast cancer cell migration and anchorage-dependent and -independent growth." (PMID 35646914, 2022). "It has been further suggested that p62 is required to recruit and activate JNK through an evolutionarily conserved VANGL2–p62–JNK signaling cascade in Xenopus and human breast cancer cells." (PMID 33824332, 2021). "This proliferative signalling cascade is upregulated in breast cancer patients with shorter survival and can be inactivated in patient-derived xenograft cells by inhibition of the JNK pathway or by disruption of the VANGL2–p62/SQSTM1 interaction." (PMID 26754771, 2016). "Over the course of our study, we have identified a peptide able to destabilize the VANGL2–p62/SQSTM1 complex, and to impair JNK signalling and cell proliferation of breast cancer cells." (PMID 26754771, 2016). "This proliferative pathway is upregulated in breast cancer patients with shorter survival and in patient-derived xenografts (PDXs), and is sensitive to inhibition of JNK and of the VANGL2–p62/SQSTM1 interaction." (PMID 26754771, 2016). "Protein extracts of breast cancer cell lines either expressing only Vangl1 (T47D, MDA-MB-231) or expressing concomitantly Vangl1 and Vangl2 (SKBR7, SUM149), were evaluated for Vangl2 expression by western blots probed with 2G4 mAb." (PMID 23029439, 2012). "The dependency evaluation of the cell lines with SCRIB, VANGL2 and NOS1AP amplifications with CRISPR and RNAi revealed several genes involved in breast cancer pathogenesis, such as FOXA1, ERBB2, PIK3CA and CDK4, to be among the top preferential essential genes." (PMID 36675340, 2023). "We found a substantial colocalization between LAMP1, VANGL2 and p62/SQSTM1 in breast cancer cells." (PMID 26754771, 2016). "This discrepancy, coupled with observations that Vangl2 is aberrantly expressed across diverse subtypes of invasive breast tumors, suggests that Wnt/PCP signaling may be a marker that could be used clinically to predict invasive or aggressive breast cancer." (PMID 37147680, 2023). "However, CRISPR and RNAi knockdown revealed no recurrent dependencies characterizing these cell lines with SCRIB, VANGL2 and NOS1AP amplifications that could suggest therapeutic avenues in breast cancers with these amplifications." (PMID 36675340, 2023). "Although Vangl1 may compensate for loss of Vangl2 in some contexts, Vangl1 transcript is not significantly altered in Vangl2fl/fl/NDL mammary tumors relative to Vangl2+/+/NDL tumors." (PMID 37147680, 2023).
breast cancer (continued). "Here, we show the nuclear localization of transmembrane, PCP protein, VANGL2, in the HCC1569 breast cancer cell line, and in undifferentiated, but not differentiated, HC11 cells that serve as a model for mammary lactogenic differentiation." (PMID 38334614, 2024). "mRNA expression of VANGL2, NOS1AP and SCRIB is not prognostic of survival in breast cancer as a whole or in the subsets of luminal A, luminal B, HER2 and basal cancers (Log Rank p corrected for multiple comparisons >0.05; not shown)." (PMID 36675340, 2023). "Vangl1 and Vangl2 fused to an N-terminal GFP tag were expressed in T47D cells, a breast cancer cell line that does not express endogenous Vangl2 at the mRNA level." (PMID 23029439, 2012).
spina bifida (17 papers, 2014 to 2025). A congenital neural tube defect in which vertebrae are not fully formed. "Conditional deletion of Vangl2 from neural plate and SE prevented elevation of the caudal neural folds and caused spina bifida, although Closure 1 occurred normally." (PMID 34842271, 2022). "Here, the authors show that mosaic deletion of Vangl2 in the murine neuroepithlium causes spina bifida by preventing apical constriction via reduced myosin II and tubulin organisation." (PMID 33608529, 2021). "In human, LoF mutations in PTK7 and the double-heterozygous mutation of PTK7 and VANGL2 were associated with spina bifida and increased the genetic risk of NTDs." (PMID 34828397, 2021). "Conditional mosaic deletion of the mammalian core PCP component Vangl2, or compound heterozygous mutations of Vangl2 and the Diaphanous-related formin Daam1, lead to spina bifida." (PMID 31182644, 2019). "Human mutations in the planar cell polarity component VANGL2 are associated with the neural tube defect spina bifida." (PMID 29590636, 2018). "In regard to this, a previous study of patients with NTDs reported a higher incidence of VANGL2 mutations in cases with closed spinal NTDs (2.5%, compared to 0.5% in open spina bifida); these cases of closed spinal NTDs with VANGL2 mutations also showed a higher prevalence of lipoma." (PMID 37589570, 2023). "To determine whether there are PTK7 and VANGL2 combined rare missense variants in human spina bifida cases, we re‐sequenced VANGL2 in the 192 spina bifida cases used in the current study (data not shown)." (PMID 30689296, 2019). "One recent publication found that knocking out VANGL2 in only 16% of the cells in the neural tube of a developing mouse embryo was sufficient to produce spina bifida." (PMID 37443734, 2023). "Increased recoil precedes failure of PNP closure and development of spina bifida in Zic2Ku/Ku embryos and in embryos with a conditional knockout in Vangl2." (PMID 31182644, 2019). "Only spina bifida is found in digenic heterozygotes at Vangl2;Ptk7, Vangl2;Grhl3, Vangl2;Sec24b, and Celsr1;Ptk7." (PMID 30134561, 2018). "One possibility (for spina bifida) is that caudal neural tube closure is delayed in some PCP-mutant heterozygotes, as has been observed in the mouse heterozygous Vangl2-Lp mutant that has 2% spina bifida." (PMID 30134561, 2018). "Unique sequence variants in both VANGL2 and CELSR1 have been previously identified in human spina bifida patients, but to the authors’ knowledge skeletal structure has not been investigated in these patients." (PMID 29463853, 2018). "Shroom3gt/gt;Vangl2+/Lp embryos exhibit exencephaly and severe spina bifida that drastically increases in penetrance to 75% (9 out of 12)." (PMID 25596276, 2015). "Genetic factors including variations in some specific genes such as MTHFR, MTHFD1, MTRR, VANGL1, VANGL2, CELSR1, and FUZ, as well as variants in the T-locus on chromosome 6q have also been studied in the development of spina bifida and other spinal dysmorphisms." (PMID 39835283, 2025). "One recent study provided evidence for this hypothesis by showing that when only 16% of cells in the mouse embryo neural tube had the NTD gene VANGL2 knocked out, spina bifida resulted." (PMID 37443734, 2023). "Nevertheless, the amplifying effect of the non-autonomous anti-morphogenetic influence of mosaic Vangl2-deletion leads to reduction in apical neuroepithelial mechanical tension and failure of neural fold elevation, causing spina bifida." (PMID 33608529, 2021). "VANGL2 gene in the 192 spina bifida cases was also sequenced, but no rare missense variant was identified." (PMID 30689296, 2019). "Finally, different individuals can have craniorachischisis or exencephaly or spina bifida in digenics heterozygous at Vangl2;Scrib or Celsr1;Scrib." (PMID 30134561, 2018).
spina bifida (continued). "At the least, our current results should encourage further studies to determine whether spina bifida and PCP mutations (including CELSR1 and VANGL2) coexist with kidney malformations." (PMID 27597235, 2016). "Shroom3+/gt;Vangl2+/Lp embryos develop spina bifida with a penetrance of 37.5% (9 out of 24)." (PMID 25596276, 2015). "Given that the locations of spina bifida lesions reflect the somite level at which PNP closure ceases, each of these examples of distal spina bifida suggest that Vangl2 is involved in late spinal neurulation, although its roles in completion of PNP closure are poorly understood." (PMID 29590636, 2018). "Alternatively, as almost all of these variants were identified in heterozygous patients, dimerization with wild type VANGL2 or VANGL1 may impair normal pathway activity with variable penetrance; a notion supported by the low incidence of spina bifida in heterozygous Vangl2 mutant mice." (PMID 37815931, 2024). "Vangl2 deletion in the Grhl3Cre domain does not significantly impair the initiation of closure or its progression until approximately the 25-somite stage, but subsequently results in spina bifida." (PMID 29590636, 2018). "It was demonstrated in mice that homozygous PCP mutations caused craniochisichisis, as shown for Vangl2, Celsr1, and Ptk7 while double heterozygosity for a PCP mutation and non-PCP mutation can cause spina bifida, as shown for Vangl2/Dact1 double heterozygotes." (PMID 24632739, 2014).
cyst (4 papers, 2014 to 2020). A sac-like closed membranous structure that may be empty or contain fluid or amorphous material. "Mutations in the PCP-associated genes Wnt9b and Fat4 have been shown to lead to cyst formation in postnatal kidneys while other murine PCP gene mutations that are homozygous lethal, like Vangl2, show early hallmarks of cyst formation such as dilated tubules." (PMID 24852369, 2014). "This work was undertaken to elucidate the role of the key PCP gene, Vangl2, in embryonic and postnatal renal tubules and ascertain whether its loss contributes to cyst formation and defective tubular function in mature animals." (PMID 32203543, 2020). "Finally, we show that loss of Vangl2 lowers expression of the polycomb group repressor Bmi1 and hinders cyst formation, while overexpression of the gene rescues cyst formation in vitro." (PMID 31068622, 2019). "We also observed this decreased viability in our cyst assay when we reduced the level of Vangl2 expression in basal cells." (PMID 31068622, 2019). "Apparently higher levels of ATMIN and VANGL2 were observed in ARPKD paediatric kidneys compared to age-matched normal kidneys, including strong expression in cyst-lining epithelia (red arrows)." (PMID 30414501, 2019).
emphysema (4 papers, 2017 to 2021). "In patients with COPD/emphysema, Wnt5a and Vangl2 expression levels are reduced, indicating an association between PCP signaling and alveolar regeneration." (PMID 34829987, 2021). "It is also notable that several independent datasets from emphysema patients, in which repair capacity is diminished, show significant downregulation of VANGL2 and WNT5A." (PMID 33195213, 2020). "VANGL2 is significantly downregulated in lung tissue from patients with emphysema." (PMID 33791298, 2021). "Vangl2 expression was inhibited in the lungs of patients with emphysema." (PMID 34829987, 2021). "Finally, we show that PCP genes VANGL2 and SCRIB are significantly downregulated in lung tissue from patients with emphysema." (PMID 28237967, 2017).
glomerular disease (4 papers, 2016 to 2021). "Collectively, the finding of VANGL2 upregulation in FSGS, coupled with the observation that glomerular disease is worsened in mice deficient for Vangl2 in podocytes, suggests that increased PCP gene expression in glomerular disease is likely to be a protective compensatory response." (PMID 30125361, 2018). "MMP9 has previously been shown to be produced by podocytes, and it is altered in several glomerular diseases, supporting the conclusion that Vangl2 modulates glomerular injury by stopping MMP9 production." (PMID 31500276, 2019). "Next, we determined whether Vangl2 plays a role in another glomerular disease model, LPS‐induced reversible glomerular injury." (PMID 30125361, 2018). "Therefore, we proceeded to investigate possible roles for Vangl2 in experimentally induced glomerular disease." (PMID 30125361, 2018). "We hypothesised that Vangl2 impacts on glomerular disease by modulating MMP." (PMID 30125361, 2018). "Experimental evidence indicating that VANGL2 regulates cytoskeletal architecture of maturing podocytes has therefore raised interest in the potential functions of this protein, or other PCP proteins, in podocyte pathology and glomerular disease." (PMID 33716764, 2021). "In addition, by interrogating microarray data from two cohorts of renal patients, we report increased VANGL2 transcript levels in the glomeruli of individuals with focal segmental glomerulosclerosis, suggesting that the molecule may also be involved in certain human glomerular diseases." (PMID 30125361, 2018). "In addition, by interrogating data from two cohorts of renal patients, we report increased VANGL2 transcript levels in glomeruli of individuals with FSGS, providing evidence that the molecule may also be involved in certain human glomerular diseases." (PMID 30125361, 2018).
invasive breast carcinoma (4 papers, 2016 to 2025). A carcinoma that infiltrates the breast parenchyma. "Elevated transcription levels of VANGL2 are associated with gene amplification in 13% of tumors in 24% of invasive breast cancers, and VANGL2 overexpression may contribute to disease progression." (PMID 39871948, 2024). "VANGL2 shows enhanced expression in 24% of invasive breast carcinomas compared to healthy tissues." (PMID 39968094, 2025).
breast tumors (3 papers, 2023 to 2024). "Based on reports that VANGL2 upregulation is associated with higher-grade breast tumors, we hypothesize that elevated VANGL2 expression and resulting activation of Wnt/PCP signaling is a feature of late-stage or advanced disease." (PMID 37147680, 2023). "To investigate this possibility, we stably overexpressed Vangl1 or Vangl2 via lentiviral infection in human and mouse breast tumor cell lines." (PMID 37147680, 2023). "In addition, a recent study showed that Vangl2 interacts with p62, subsequently promoting breast tumors by activating JNK signaling." (PMID 39269442, 2024). "Collectively, our observations demonstrate for the first time that Vangl2-mediated Wnt/PCP signaling is critical to metastatic dissemination of breast tumor cells, likely through the promotion of local collective cell migration and invasion from the primary tumor." (PMID 37147680, 2023). "Expression analysis of patient-invasive breast tumors suggests that Vangl2 dysregulation is a feature common to breast tumors rather than being associated with a single molecular subtype." (PMID 37147680, 2023).